ENSG00000239041
Synonyms: LOC124906146
Gene: Small nucleolar RNA gene on chromosome 2 (172,691,299 to 172,691,402, forward strand). Ensembl gene ENSG00000239041.
Gene Ontology:
Biological process: RNA processing
Cellular component: nucleolus
Homologues: Paralogues in human: SNORD13D (86% identical), SNORD13P1 (85% identical), SNORD13 (83% identical), SNORD13P3 (82% identical), SNORD13E (80% identical).